ITPA (inosine triphosphatase)
Diseases named in the same sentence as ITPA in open-access papers (continued):
Sharing a sentence is not in itself a finding about the gene and the disease.
cancer (7 papers, 2012 to 2025). A tumor composed of atypical neoplastic, often pleomorphic cells that invade other tissues. "Conversely, overexpression of ITPA has been reported in various cancer cell lines, such as colon, lung, liver, pancreatic, and brain." (PMID 27779101, 2016). "Overall, the findings from this study suggest that ITPA is an important factor in the maintenance of genome stability and protection from the onset of therapy-induced degenerative diseases and cancer." (PMID 22384212, 2012). "Since cancer cells replicate DNA at a faster rate than normal cells, cancer may be more hypersensitive to ITPA malfunctions." (PMID 36899424, 2023). "The study concluded that absence of functional ITPase activity caused by ITPA gene defects may lead to DNA damage and cancer as a consequence of the accumulation of non-canonical nucleotides." (PMID 23547827, 2013). "Further evidence has been provided by a recent in vitro study on human HeLa cells, with a knockdown ITPA gene, which showed that the absence of functional ITPase activity can lead to accumulation of non-canonical nucleotides which may cause DNA damage and cancer." (PMID 23547827, 2013). "Finally, cell experiments confirmed that ITPA gene knockdown in UVM cell lines could significantly inhibit the activity and proliferation and invasion ability of cancer cells." (PMID 35242144, 2022).
infection (7 papers, 2014 to 2022). The state of being infected such as from the introduction of a foreign agent such as serum, vaccine, antigenic substance or organism. "Further testing showed genotype 1b CHC infection, interleukin (IL) 28B C/T and inosine triphosphatase (ITPA) CC/AA genotypes, and a low viral load (HCV RNA 53049 IU/mL; HCV Abbott RealTime PCR version 4.0, lower limit of quantification 12 IU/mL; Abbott GmbH & Co., Wiesbaden, Germany)." (PMID 24650206, 2014). "In 2010, a genome-wide association study revealed that two functional variants in the inosine triphosphatase (ITPA) gene causing ITPA deficiency protect against RBV-induced hemolytic anemia and the need for RBV dose reduction in patients with HCV genotype 1 infection." (PMID 25227310, 2014). "This may be an effect of ITPA siRNA not being able to completely silence expression of ITPA RNA or a result of the current experimental cell culture infections being standardized to 72 h." (PMID 30045981, 2018).
tumor (3 papers, 2013 to 2022). "The mRNA expression level of ITPA was proved to be higher in tumor cells than those in normal tissues, showing preferentially expressed in tumor cells." (PMID 28099906, 2017). "KDELR3 was mainly expressed in tumor cells, IDH2 was mainly expressed in endothelial cells, S100A6 was mainly expressed in photoreceptor cells, ITPA was mainly expressed in endothelial cells and tumor cells, PARP8 was mainly expressed in T cells, and APRC1B was mainly expressed in endothelial cells." (PMID 35242144, 2022).
hematological disease (1 paper, 2013). "Interestingly, ITPA has been mentioned in relation to hematological disease where it has been noted as one of five mixed-lineage leukemia associated genes whose up-regulation accompanies amplification of the MLL gene region of 11q23." (PMID 23547827, 2013).
ITPA also shares sentences with these, for which no sentence is quoted: Epileptic encephalopathy (3 papers); pancreatitis (3); epilepsy (2); fibrosis (2); Infantile encephalopathy (2); acute myeloid leukemia (1); anxiety disorder (1); congenital cataracts (1); degenerative diseases (1); genetic disorder (1); heart failure (1); influenza (1); juvenile idiopathic arthritis (1); Martsolf syndrome (1); myopathy (1); neurological disorders (1); Obesity (1); pancreatic adenocarcinoma (1); pancreatic cancer (1); veno-occlusive disease (1).